SF1 (splicing factor 1)
Diseases named in the same sentence as SF1 in open-access papers (continued):
Sharing a sentence is not in itself a finding about the gene and the disease.
endometriosis (21 papers, 2007 to 2026). The growth of functional endometrial tissue in anatomic sites outside the uterine body. "The abnormal expression of SF-1 in endometriosis may be caused by epigenetic modifications determined primarily by the methylation of its promoter." (PMID 32370117, 2020). "In addition to interaction with methylating enzymes, interaction with demethylating enzymes, such as DNA methyltransferases (DNMT3B), may be the cause of abnormal expression of SF-1 in endometriosis." (PMID 32370117, 2020). "As shown by previous studies, SF-1 is overexpressed in stromal cells from endometriotic tissues compared to eutopic endometrial tissues, contributing substantially to endometriosis." (PMID 40792071, 2025). "TCF21 interacts with USF2 in endometriotic stromal cells and activates the promoters of SF-1 and estrogen receptor beta, thereby influencing the estrogen pathway in endometriosis." (PMID 40182431, 2025). "In the same line, the cooperation between GATA6 and SF-1 is reported to be sufficient for endometriosis development and persistence." (PMID 40792071, 2025). "In sum, the effects of gamma-oryzanol as a therapeutic agent to alleviate pathogenesis of endometriosis in rats were investigated by the protein level of ER-α, SF1, SIRT1, HO-1, LC3 and BECN1." (PMID 35181729, 2022). "Steroidogenic factor-1 (SF1) regulates the transcription of multiple genes involved in estrogen biosynthesis and is upregulated in endometriosis." (PMID 34638843, 2021). "Inhibition of ERβ, SF-1, and aromatase can decrease the production and function of local estrogen, thus leading to alleviation of endometriosis." (PMID 34531822, 2021). "As a transcriptional regulator, circulating miR-370-3p was demonstrated to repress cell proliferation by downregulating steroidogenic factor 1 (SF1) in endometriosis." (PMID 32112646, 2020). "Aberrant demethylation of the SF-1 promoter in endometriosis results in the upregulated expression of SF-1." (PMID 32370117, 2020). "Epithelial cells obtained from endometriosis endometria had high SF-1 protein expression in basal condition, which were resistant to E2 and PGE2." (PMID 26453052, 2015). "The SF-1 gene promoter in endometriosis is specifically hypomethylated in peritoneal endometriosis." (PMID 40792071, 2025). "Epigenetic silencing of SF1 is lost in endometriosis due to hypomethylation of NR5A1." (PMID 40792071, 2025). "Suppressing FOXP1 reverted the endometrium cell phenotype, involving decreased collagen gel contraction, cell growth and migratory movement.TCF21 could transactivate SF-1 and Erβ promoters in ESCs, modulating estrogen pathway and fibrosis of endometriosis." (PMID 38844959, 2024). "It has been found that methylation of CpG islands in the SF-1 gene, which spans from exon II to intron III, positively regulates its expression in EnSCs in endometriosis, whereas hypomethylation of SF-1 gene CpG islands in eutopic endometrium drastically decreases SF-1 levels." (PMID 37569571, 2023). "Abnormal DNA methylation in endometriosis then affects the expression of several genes, including homeobox A10, estrogen receptor, progesterone receptor, steroidogenic factor 1 (SF-1), and aromatase." (PMID 36974156, 2023). "The change in expression of estrogen receptor-β (ERβ), progesterone receptor (PR), transcriptional factors such as GATA-6 binding factor, SF-1 in endometriotic stromal cells seems to account for estrogen dependency and progesterone resistance, characteristic for endometriosis." (PMID 35409163, 2022). "Therefore, the present work assesses the effects of GO in rat models with surgically induced endometriosis, by evaluating the western blotting expression of ER-α, SF1, SIRT1, HO-1, LC3B, BECN1." (PMID 35181729, 2022). "SF-1 downregulation via miR-370-3p could be a new strategy for controlling endometriosis proliferation." (PMID 34638843, 2021).
endometriosis (continued). "In addition, steroidogenic factor-1 (SF-1; encoded by NR5A1) and aromatase (encoded by CYP19A1) are also overexpressed in the ESCs of patients with endometriosis." (PMID 34531822, 2021). "Taken together, the results show that 120 μg/mL EVs derived from UC-MSCs can effectively inhibit the proliferation and invasion of ESCs, as well as their expression of SF-1, ERβ and aromatase, and thus may lead to the alleviation of endometriosis." (PMID 34531822, 2021). "EVs derived from UC-MSCs can effectively inhibit the proliferation and invasion of ESCs, as well as the expression of SF-1, ERβ, and aromatase, thereby restricting the growth, invasion, and estrogen levels of ectopic lesions, thus leading to the alleviation of endometriosis." (PMID 34531822, 2021). "Considering the pivotal role of transcription factor in endometriosis, investigating the regulators of SF-1 may open a novel strategy for treatment of the disease." (PMID 32370117, 2020). "The mechanisms that regulate SF-1 expression in endometriosis are not fully understood." (PMID 32370117, 2020). "Nevertheless, SF-1, expressed in eutopic and ectopic endometria from women with endometriosis, aberrantly activates CYP19A1 and the expression of P450Arom in stroma or gland in these tissues as has been extensively described favoring this estrogenic microenvironment in this disease." (PMID 26453052, 2015). "Endometriosis, pro-inflammatory and invasive benign disease estrogen dependent, abnormally express in endometria the enzyme P450Arom, positively regulated by steroid factor-1 (SF-1)." (PMID 26453052, 2015). "Interestingly, hypomethylation and subsequent transcriptional activation of SF-1 has been reported in endometriosis, an estrogen dependent disease." (PMID 23291911, 2013). "Endometriosis has been recognized as a disease accompanied by aberrant methylation and expression of steroidogenic factor-1 (SF-1), estrogen receptor 2 (ESR2), progesterone receptor (PR-B) and HOXA10 genes in the eutopic endometrium of women with endometriosis." (PMID 22233680, 2012). "Overexpression or overactivity of SF-1 is also reported in some adrenal tumors or endometriosis." (PMID 21078366, 2011). "Our results showed that GO is involved in decreasing the pathogenesis of induced endometriosis by influencing on BECN1 and SF1, and also inducing apoptosis in rats." (PMID 35181729, 2022). "Nevertheless, in endometriosis cells, the high USF2, SF-1 and P450Arom protein contents in basal condition were unmodified." (PMID 26453052, 2015). "The genes of ER-α, SF1, SIRT1, HO-1, LC3B, and BECN1 are involved in the endometriosis." (PMID 35181729, 2022). "In fact, methylation of CpG islands in the SF-1 gene, which spans from exon II to intron III, positively regulates its expression in stromal cells present in endometriosis, whereas hypomethylation of SF-1 gene CpG islands in normal endometrium is associated with drastically lower SF-1 levels." (PMID 33411206, 2021). "Although two types of USF, USF1 and USF2, have been reported, it is USF2 that shows the highest binding activity on SF-1 promoter and its knockdown results in down-regulation of SF-1 and also of its target gene CYP19A1 in ectopic endometrium from endometriosis women." (PMID 26453052, 2015). "Hypomethylation of SF-1 and ESR2 promoters may be responsible for increased estrogen action in women with endometriosis." (PMID 22233680, 2012). "Given the elevated adrenergic receptor expression in endometriotic lesions and the potential of terazosin to downregulate Steroidogenic Factor-1 (SF-1), this study aimed to evaluate terazosin as a non-hormonal therapy in a surgically induced rat endometriosis model." (PMID 42123670, 2026). "Such increased SF-1 expression or activity in endometriotic tissue could result in increased activity of steroid acute regulatory protein (StAR) and aromatase (CYP19A1), resulting in increased local estrogen biosynthesis, a key pathological feature of endometriosis." (PMID 32370117, 2020).
adrenocortical carcinoma (20 papers, 2007 to 2025). "Another study found that the expression of an SF-1 target gene encoding the guanine exchange factor VAV2 was a critical mediator of changes in adrenocortical carcinoma cell morphology that promoted invasion in both culture and in vivo models." (PMID 36650372, 2023). "NOV, encoding a secreted pro-apoptotic factor for adrenocortical cancer cells, is an example of those genes that are tightly regulated according to SF-1 dosage." (PMID 23907384, 2013). "SF-1 has also been implicated in adrenocortical carcinoma, a rare and deadly cancer." (PMID 37328104, 2023). "As for Ftz-F1 orthologs, the human liver receptor homolog-1 (LRH-1) has been associated with colonic, gastric, breast and pancreatic cancer, whereas steroidogenic factor 1 (SF-1) has been implicated in prostate and testicular cancers and in adrenocortical carcinoma." (PMID 26398940, 2015). "In addition, multiple studies have also confirmed that SF-1 has a high value in the diagnosis of adrenocortical carcinoma and the prognosis evaluation of patients, and it has been reported that SF-1 overexpression is associated with a low survival rate in patients with adrenocortical carcinoma." (PMID 35983531, 2022). "Conversely, SF-1 overexpression is associated with increased adrenocortical tumor cell proliferation, development of adrenocortical tumors in mice and is a widespread finding in pediatric adrenocortical tumors, whereas it confers a more severe prognosis to adult adrenocortical cancers." (PMID 23907384, 2013). "In adrenocortical carcinoma, the steroidogenic factor 1 (SF-1), a nuclear receptor pivotal for adrenal development and steroidogenesis, also plays a role in tumour invasiveness and proliferation." (PMID 41226387, 2025). "On the other hand, SF-1 overexpression is found in adrenocortical carcinoma and represents a prognostic marker for patients’ survival." (PMID 36835002, 2023). "We have reported the first case of aldosterone-producing adrenocortical carcinoma diagnosed solely by immunohistochemical staining for adrenocortical-specific Ad4BP/SF1 and steroidogenic enzymes in a metastatic liver tumor." (PMID 26772981, 2016). "Mice harboring multiple copies of Sf1, mimicking the amplification of Sf1 seen in childhood adrenocortical carcinoma, develop adrenocortical neoplasms that express gonadal-like markers." (PMID 25798129, 2015). "An unexpected result of our study is represented by the discovery of a functional interaction of SF-1 with the transcription factor NRSF/REST in regulating gene expression in adrenocortical cancer cells." (PMID 23907384, 2013). "On the other side of the spectrum, SF-1 overexpression increases adrenocortical cancer cell proliferation and induces adrenocortical tumor formation in mice and in humans is associated to adrenocortical tumorigenesis both in children and adults." (PMID 23907384, 2013). "Adrenal cortical tumors frequently test positive for SF-1 and inhibin." (PMID 39290924, 2024). "Therefore, SF-1 is an attractive therapeutic target for disease states characterized by dysregulation of steroidogenesis and energy homeostasis as well as adrenocortical carcinoma." (PMID 37328104, 2023). "To identify the genes regulated by SF-1 in human adrenocortical cancer cells, we performed knockdown and overexpression experiments in the H295R/TR SF-1 cells, a subclone of the H295R cell line where SF-1 overexpression can be induced in a doxycycline-dependent manner." (PMID 23907384, 2013). "In conclusion, we have shown here that SF-1 regulates distinct categories of genes in adrenocortical cancer cells according to its dosage and that binding of the factor to chromatin sites in conditions of different SF-1 dosage correlates with differential regulation of gene expression." (PMID 23907384, 2013).
adrenocortical carcinoma (continued). "Finally, the SF-1 gene profile can be used to distinguish malignant from benign adrenocortical tumors, a finding that implicates SF-1 in the development of malignant adrenocortical carcinoma." (PMID 22427816, 2012). "High levels of SF-1 were also reported in adrenocortical carcinoma (ACC) in adults and negatively correlated to patients’ overall survival (OS)." (PMID 36835002, 2023). "Finally, SF-1 antagonists are sought for the treatment of adrenocortical cancer, and this structure may yield strategies to modify 6N-10CA for receptor destabilization and antagonism." (PMID 37328104, 2023). "Expression of master-regulator SF1 and the key adrenal transcription factors GATA4 and GATA6 in the HAA1 line was present, but lower than that in the control NCI-H295R human adrenal cortical carcinoma cell line." (PMID 36614027, 2022). "Here, we have shown that SF-1 and NRSF/REST functionally interact in regulating gene expression in H295R adrenocortical cancer cells." (PMID 23907384, 2013). "In adrenocortical carcinoma, FSCN1 is required for SF-1/VAV2-driven cell invasion." (PMID 41226387, 2025). "Independent of its steroidogenic actions, SF-1 promotes the proliferation and invasion of adrenocortical carcinoma cells." (PMID 36650372, 2023). "The two sarcomatoid adrenocortical carcinomas in our series did not stain for SF-1 which suggests a possible de novo pathway of tumorigenesis for this rare variant." (PMID 25889798, 2015). "In an effort to elucidate the roles of SF-1 and RNF31 in adrenal steroidogenesis and adrenocortical carcinoma on a genome-wide level, we performed siRNA-mediated knockdown of SF-1 or RNF31 ± cAMP in the adrenocortical carcinoma cell line NCI-H295R." (PMID 22427816, 2012). "A concomitant Western-blot analysis revealed markedly higher SF-1 protein levels in atrazine-responsive H295R adrenocortical carcinoma cells compared with the nonresponsive KGN granulosa cells." (PMID 17520059, 2007). "Furthermore, negative results for SF-1, inhibin alpha, c17, DHEAST, and 3BHSD ruled out adrenocortical carcinoma metastasis." (PMID 34797454, 2021).
adrenocortical tumor (20 papers, 2013 to 2024). "Sustained elevated expression of Sf1 has been implicated in conditions such as childhood adrenocortical tumours." (PMID 31320667, 2019). "Steroidogenic Factor-1 (SF-1) is a nuclear receptor that has a pivotal role in the development of adrenal glands and gonads and in the control of steroid hormone production, being also implicated in the pathogenesis of adrenocortical tumors." (PMID 23907384, 2013). "SF-1 overexpression leads to increased cell proliferation in the mouse definitive adrenal cortex and in the H295R adrenocortical tumor cell line." (PMID 36835002, 2023). "Overexpression of NR5A1/SF-1 inhibited multiple centrosomes during prolonged replication stress in adrenocortical tumor cells." (PMID 34208028, 2021). "To explore the possibility that Ad4BP/SF-1 is involved in cholesterogenic gene regulation, we obtained the transcriptomes of Y-1 cells, which are derived from a mouse adrenocortical tumor." (PMID 30271905, 2018). "Accordingly, here, we analyzed the expression of the SF-1 gene after downregulation of endogenous POD1 expression in pediatric adrenocortical tumor cells." (PMID 28658440, 2017). "Interestingly, SJ-ACC3 displayed a highly significant overexpression of SF-1 RNA and protein, which is in accordance with previous reports on childhood adrenocortical tumors." (PMID 27764813, 2016). "POD-1/TCF21 may play a crucial role in adrenal and gonadal homeostasis and represses Sf-1/SF-1 expression in adrenocortical tumor cells." (PMID 26421305, 2015). "Thus, it could be reported that TCF21 is downregulated in ACC and regulates the steroidogenic factor 1 (SF-1) and StAR protein (steroidogenic acute regulatory protein) binding to the SF-1 E-box promoter in adrenocortical tumor and normal adrenal cells." (PMID 35201460, 2021). "In human adrenocortical tumor cells, TCF21 inhibits the expression of endogenous SF-1 and the SF-1 target gene StAR through binding to the E-box sequence of SF-1 promoter." (PMID 27028856, 2016). "First, the determination of steroidogenic factor 1 (SF-1) expression represents the most valid marker to distinguish between primary adrenocortical tumors and non-adrenocortical tumors." (PMID 33260476, 2020). "In order to assess whether POD-1 can regulate LRH-1 via the same mechanism that regulates SF-1, we analyzed the endogenous mRNA levels of POD-1, SHP, and LRH-1 in hepatocarcinoma and adrenocortical tumor cells using qRT-PCR." (PMID 26421305, 2015). "In human adrenocortical tumor cells, we found that POD-1 binds to the SF-1 E-box promoter sequence and inhibits SF-1 expression, as well as the expression of StAR protein, which is controlled by SF-1." (PMID 26421305, 2015). "However, SF-1 is not widely available or used, but inhibin-negative immunohistochemistry can be observed in some adrenocortical tumors." (PMID 39290924, 2024). "SF-1, also known as Ad4-binding protein or NR5A1, binds as a monomer to nuclear receptor half sites on DNA, and it plays an important role not only in adrenal steroidogenesis but also in cell adhesion, cell proliferation, apoptosis, and angiogenesis of adrenocortical tumor cells." (PMID 33981288, 2021).